CD4 (CD4 molecule)
Diseases named in the same sentence as CD4 in open-access papers (continued):
Sharing a sentence is not in itself a finding about the gene and the disease.
tumor (continued). "The digital pathology analysis with artificial intelligence-based algorithms was used to detect and count tumor cells and cellularity, and B vs. T cells (both CD4 and CD8 positive cells) in terms of IHC marker expression and spatial distribution." (PMID 37086293, 2023). "Almost half of the tumours were CD4-excluded (45.3%) and the remaining split into hot (28.3%) and cold (26.4%) tumours." (PMID 36726072, 2023). "ABI3BP was associated with an increase in B cell, T cell CD4+, T cell CD8+, Macrophage, and Neutrophil infiltration of tumor cells, as determined by additional analyses of immune infiltration." (PMID 37197424, 2023). "We also characterized the overall CD4+ T cells in PBMCs harvested from TC-1 tumor-bearing mice on day 32 after the TC-1 tumor cell challenge in groups treated with pBI-11 DNA delivered through different routes of administration versus untreated." (PMID 37791765, 2023). "Our work shows that CD4 CTLs can potently kill tumors and can independently mediate tumor regression, but there are limitations." (PMID 37185301, 2023). "While CD8 and Th1 CD4+ T cells tend to mostly play an anti-tumor role, they also rely on external signaling to amplify their anti-tumor response in the TME." (PMID 37892917, 2023). "CD4+ cells are instead associated with better survival in patients with LBO, highlighting their protective effect in regard to tumor progression." (PMID 36831348, 2023). "Conventional DCs (cDCs) at early malignancy recognize dying tumor cells and migrate to draining lymph nodes (DLNs) to present tumor antigens to CD4+ and CD8+ T cells." (PMID 37275901, 2023). "Following the delivery of IL-12 with FUS + microbubbles, flow cytometry analysis reported an upregulation of T lymphocyte population, including CD3+ and CD4+, which correlated with impairment of tumor growth compared to IL-12 administration alone." (PMID 38164436, 2023). "100% of mice that received CD4 T cells from ITI-3000-immunized WT mice showed delayed tumor kinetics and enhanced survival (p = 0.0003)." (PMID 37711623, 2023). "Intratumoral delivery of IL-12 in combination with CAR T cells also showed increased infiltration of Th1-like CD4+ T cells into the tumor microenvironment." (PMID 36980536, 2023). "Although to a lesser extent, the CD4 T-cell proportion also was higher in DLBCL than in control samples (tumor/spleen fold change: 1.3e+01, p ≤1.0e-6)." (PMID 37205092, 2023). "Chronic exposure to tumor antigens induces dysfunction in CD4+ T cells, distinct from the exhausted phenotype observed in CD8+ T cells." (PMID 37892995, 2023). "Surprisingly, we demonstrated that RIME KO decreased the proportion of pro‐tumour M2 macrophages in ESCC xenografts while increasing CD4+ T cells and anti‐tumour M1 macrophages proportion in ESCC xenografts." (PMID 37712124, 2023). "If UBL3 can cause infiltration of DCs CD4+ and CD8+ in tumors, which, in turn, enhances the body’s immune response to tumor cells, this would address the problem of tumor immunosuppression from another perspective." (PMID 36674743, 2023). "The results of the IHC analysis showed that the level of CD4 expression in the tumor sample is elevated compared to the normal sample." (PMID 38035067, 2023). "Tumour biopsies showed increasing numbers of tumour infiltrating CD4+ and CD8+ lymphocytes, indicating an immune response, as well as persistently low numbers of FOXP3+ Treg, indicating decreased immune suppression within the TME." (PMID 37686020, 2023). "The results showed that PAMscore was significantly negatively correlated with tumor immune cells CD4 + T cells and CD8 + T cells, and other immune cells were mostly positively correlated with PAMscore." (PMID 37202800, 2023). "The PD‐L1 protein in GCs of this study were mostly expressed in tumor‐infiltrating immune cells and strong PD‐L1 expression was associated with higher infiltration of M2 macrophage, CD8 T cells, and CD4 T cells." (PMID 36916290, 2023).
tumor (continued). "We observed only very few significant changes in the transcriptomic profiles of CD4+ T cells between tumor center and periphery." (PMID 38127790, 2023). "In response to the cytokine milieu in the tumor microenvironment, naïve CD4 T cells can differentiate into several T helper subsets with very divergent effects on antitumoral immune responses." (PMID 36980536, 2023). "In the tumor microenvironment, GCs acted on CD4+ regulatory T cells to enhance their immunosuppressive function and promote tumor growth." (PMID 37712416, 2023). "T-bsAbs are known to recruit T cells to the tumor and cause MHC-unrestricted killing of cancer cells by both CD8 + and CD4 + T cells, which enables neoantigen release and thus a potential expansion of neoantigen-specific T cells." (PMID 37118819, 2023). "An inhibitory VISTA antibody reduced the emergence of tumor-specific Foxp3+CD4+ Tregs, and suppressed tumor growth in melanoma." (PMID 37190254, 2023). "On the one hand, tumor cells can maintain memory T cells and persistent antigens at a relatively low level, which mediates CD4+ and CD8+ related responses." (PMID 36839774, 2023). "The main lymphocyte subgroups involved in anti-tumor immunity, including CD4 + Tcm, CD4 + Tem, and CD8 + T cells, showed a significant increase in the CCNB1 low expression group." (PMID 37592341, 2023). "Here Schoenberger and colleagues analyze an oligoclonal CD4+ T cell response to a naturally arising murine tumor NeoAg at the level of TCR usage and functionality." (PMID 37400675, 2023). "The TIME consists mainly of tumor associated macrophages (TAM), myeloid-derived suppressor cells (MDSC), CD4- CD8- T cells, B lymphocytes, NK cells, DCs, stromal and endothelial cells." (PMID 36776840, 2023). "The results showed that tumor-bearing mice treated with TIL CAR-T cells had more infiltration of CD4+ and CD8+ T cells than those in the other groups." (PMID 38067271, 2023). "Following antigen uptake, cDC2s migrate to tumor-draining LNs, where they directly prime CD4+ T cells or transfer antigens to resident DCs." (PMID 36949244, 2023). "In the context of cancer, multiple lines of evidence highlight the importance of CD4+ T cell recognition of tumor antigens for cancer immunotherapy responses." (PMID 37744350, 2023). "Our results demonstrate that an effective immune response to ICI involves activation of tumor reactive CD4 and CD8 T cells by antigen presenting B cells, in the context of TLS in the TME." (PMID 37435085, 2023). "Overall, these data suggest that adoptively transferred TSCM-like CD4+ T cells recognizing CLTCH129>Q are actively involved in the priming of tumor-specific CD8+ T cells in the tdLNs." (PMID 37400675, 2023). "Conventional DC (cDC) 1 induced the anti-tumor immune response of killer T cells and improved the survival rate of cancer patients, while cDC2 induced the anti-tumor immune function of CD4+ T cells." (PMID 36865562, 2023). "The population of T cells was also regulated upon rivaroxaban treatment, reducing the immune-suppressive regulatory CD4+ FoxP3+ T cells and increasing tumor-killing granzyme B+ CD8 T cells." (PMID 37444590, 2023). "For the tumor region and IM together, higher CD4+ (DFS, P=0.0156; OS, P=0.0121) and CD19+ (DFS, P=0.0206; OS, P=0.0309) signals were significantly correlated with better survival." (PMID 37090736, 2023). "PIK-93 combined with anti–PD-L1 antibodies suppresses tumor growth and increases the recruitment of tumor-infiltrating CD4+/8+ T cells to the TME in both mouse models." (PMID 37027467, 2023). "Here, we integrated bulk and single-cell transcriptome gene expression data in TIGER to comprehensively explore the anti-tumor immunity of CD4+ T cells under immunotherapy." (PMID 36049666, 2023). "CD69+ expression was significantly increased on CD8+ and CD4+ T cells both within the tumor and spleen." (PMID 37426447, 2023).
tumor (continued). "We found that POSTN+ CAFs tended to encircle the tumour nests and infiltrated CD4+ T cells and CD8+ T cells located mostly in the stromal regions formed by multi‐layers of POSTN+ CAFs." (PMID 38115703, 2023). "Even though Treg only stands for 5% of CD4+ T lymphocytes in the blood circulation of healthy donors, their abundance increases in the tumor microenvironment (TME) of BC." (PMID 38083903, 2023). "As one of the markers of the immunosuppressive tumor microenvironment, the proportions of regulatory T cells (CD4+Foxp3+ T cells, Tregs) in the tumor tissues of the saline and the Cap groups reached 134.2 and 98.16 per milligram of tumor, respectively." (PMID 37550297, 2023). "Conversely, PDA primary tumors had greater PD-1+ICOS- CD8+ TRM (CP5) and PD-1hiTIGIT+CD57+ senescent CD4+ memory T cells (C4), suggesting a more chronic exhausted and/or senescent state in the primary tumor compared to liver metastasis." (PMID 36798126, 2023). "The vaccine, administered with poly-ICLC, was first injected to 19 patients involved in this trial, with 84.6% of them showing tumor-peptide specific CD4 + T-cell responses and a median OS of 19 months." (PMID 37046332, 2023). "In patient P03, the distribution pattern of spatial T cells switched after nAde, recruited tumor-reactive T cells such as PD-1+ CD8+ T cells and suppressive FOXP3+ CD4+ Treg cells were distributed in the tumor margin and rarely infiltrated into tumors." (PMID 37488287, 2023). "Following tumor insult, naive mice showed a comparable prevalence of CD4+ T cells to their survivor counterparts and a significantly higher percentage of CD8+ T cells." (PMID 37345658, 2023). "The tumor microenvironment (TME) of MSI CRC tumors includes a higher number of tumor-infiltrating lymphocytes (TILs), including T helper 1 (Th1) CD4+ and cytotoxic CD8+ T cells, as well as antigen-presenting cells (APCs)." (PMID 36765821, 2023). "TLSs are often located outside tumor nests, with higher densities of B cells and CD4+ T cells than inside or around tumors." (PMID 37187731, 2023). "The direct cytotoxic potential of CD4+ T cells in the TME has been shown in human cancers where tumor-specific CD4+ T cells portray similarities to classical CTLs." (PMID 37304294, 2023). "Once they reach the tumor, the CD4+ T-cells release cytokines like IFNγ and TNF to enhance the cytotoxic CD8+ T-cell-mediated response, strengthening the antitumor immune response." (PMID 38002256, 2023). "ACM derived from OGJ patients with early-stage tumours and late-stage tumours increased the frequency of central memory CD4+ T cells compared with untreated cells (untrx: 7.35 ± 0.5 vs. early-stage: 11.39 ± 1.0, p = 0.07 late-stage: 10.66 ± 1.0%, p = 0.02)." (PMID 36790524, 2023). "Increased tumor-infiltrating CD4+ T cells and increased Estrogen receptors alpha (ERα) expression were identified in NF-κB active tumors." (PMID 37523561, 2023). "Most tested cancer types exhibited a notable degree of motility for both CD8+ and CD4+ Temra cells between blood and normal or tumor tissues." (PMID 37063862, 2023). "In recent years, however, it has been found that CD4+ T cells also play an important role in tumor killing." (PMID 37649123, 2023). "The level of H3K79me2 in tumor-infiltrated CD4 T cells was higher in SLC43A2 KO B16F10-bearing mice than in SLC43A2-intact B16F10-bearing mice." (PMID 37147330, 2023). "This combined treatment notably elevated CD4+ T-cell presence within the tumor microenvironment and increased IL-5 and IL-13 tumor levels, while simultaneously decreasing CD38 in the tumor stroma." (PMID 37689790, 2023). "Tregs, which contribute to immunosuppression and tumor progression, are a vital subpopulation of CD4+ T cells." (PMID 37187731, 2023). "Tumor-infiltrating lymphocytes (TILs) comprise different subtypes of lymphocytes with high immunogenicity against tumor cells CD4+, CD8+, CD20+ and FoxP3+ TILs." (PMID 37190214, 2023).
tumor (continued). "In colorectal cancer (CT26) BALB/c models, combination of the AOS001F/5-FC with anti-PD-1 therapy resulted in both an elevated CD4+ T cells at the tumor site and an increased the CD8/T reg ratio." (PMID 37514190, 2023). "The main two tumor-infiltrating lymphocyte (TIL) cell populations that mediate adaptive immunity are T cells (CD4+ and CD8+) and B cells." (PMID 38263981, 2023). "ILC3 secretes chemokine CXCL10 inside the tumor, which encourages antitumor immune responses by recruiting CD4+ and CD8+ T cells." (PMID 37937304, 2023). "The BTC tumor edge serves as the primary location for active infiltration by FOXP3+CD4+ Tregs that express elevated levels of lymphocyte activation gene 3 (LAG-3) and T cell immunoglobulin and mucin domain-containing protein 3 (TIM3)." (PMID 38213535, 2023). "B cells are responsible for the production of antibodies that favor an anti-tumor response by promoting tumor killing by NK cells, phagocytosis by macrophages, and the priming of CD4+ and CD8+ T cells." (PMID 37104271, 2023). "Tumor‐infiltrating immune cells were assessed by mIHC using IHC markers for CD4 T cells, CD8 T cells, regulatory T cells, NK cells, M2 macrophages, and B cells." (PMID 36916290, 2023). "cDC1 have been implicated in the activation of antitumor cytotoxic CD8+ T cells and T cell migration to tumor while cDC2 are important for the activation of CD4+ T cells including Tregs67." (PMID 37041154, 2023). "Here the authors show that B7-H3 expression is dependent on mTORC1 activity and that inhibition of B7-H3 promotes antitumor immunity mediated by cytolytic CD4 + T cells in tumor models with mTORC1 hyperactivity." (PMID 36869048, 2023). "Second, mouse tumor specimens were assessed for IL-2, IL-10, and CD4 levels by immunohistochemistry." (PMID 37253929, 2023). "In these mouse models, CD4+ T-cells in the tumour microenvironment were necessary for tumour formation." (PMID 36836878, 2023). "ACM derived from OGJ patients with late-stage tumours significantly decreased the expression of CD69 on the surface of CD4+ T cells compared with untreated cells (untrx: 7.43 ± 0.8 vs. late-stage: 4.29 ± 1.1%, p = 0.005)." (PMID 36790524, 2023). "Accumulating studies have revealed that CD4+ T cells can directly cause tumor cell lysis by cytotoxicity and dictate the host responses to ICI therapy, assigning CD4+ T cells as extremely plastic players." (PMID 38062068, 2023). "We firstly tested immunologic markers of CD4+, CD8+, CD68+, FOXP3+, PD‐L1+, CD4+FOXP3+, CD4+FOXP3−, CD68+PD‐L1+, CD68+PD‐L1−, CD8+PD‐L1+, and CD8+PDL1− in the tumor core area, tumor‐associated stroma area, and total area before NAC." (PMID 36043478, 2023). "FoxP3 regulatory T cells are an immunosuppressive subpopulation of CD4+ T cells that modulate the anti-tumor response mediated by CD8+ T cells." (PMID 37104271, 2023). "The second group consists of tumor-promoting immune cells, including CD4+CD25+ T cells (Tregs), myeloid-derived suppressor cells (MDSCs), and mast cells." (PMID 37545500, 2023). "Other authors have found CCL11 protein increases the proportion of CD4 + CD25 + Foxp3+ Treg cells, the expression of CCR3 and Foxp3, and the release of IL2 and TGFβ1 in non-tumour-associated CD4+ T cells via the STAT5 signalling pathway." (PMID 37626783, 2023). "Several in vitro studies postulate eosinophils mediate tumor destruction via crosstalk with B-cells, Th1 and Th2 CD4+ T cells, and granulocytes." (PMID 36427017, 2023). "The large panels used in mass cytometry give the possibility to map the relationships between different cell populations and shift the focus on other cell types that enhance anti-tumor response such as CD4+ T cells." (PMID 36414693, 2023). "Within the tumor microenvironment, we found that inhibition of TLR1/2 by the small molecule CU-CPT22 dramatically decreased the effect of OXP, leading to fewer tumor-infiltrating immune cells, including CD4+, CD8+ and IFNγ+ CD8+ cells." (PMID 37945630, 2023).
tumor (continued). "Cytokine expression was critical in the MOA of ITI-3000 as CD4 T cell-mediated IFNγ production was essential for the anti-tumor immune response induced by vaccination." (PMID 37711623, 2023). "With the combination of αTim-3 with S100, CD4+ T were unleashed, and anti-tumor immunity was significantly enhanced." (PMID 37771774, 2023). "At tumor sites, exhausted phenotypes of CD4+ and CD8+ T cells (defined as PD1+, TIM3+, LAG3+ T cells) are higher than those detected in matched peripheral blood mononuclear cells." (PMID 37444531, 2023). "CD4+ T cell-derived IFNγ can either act on tumour cells or through IFN-dependent activation of iNOS-expressing tumouricidal myeloid cells." (PMID 37316667, 2023). "Dense CD4+ lymphocytic infiltration in the invading front is related to high tumor-budding (TB) (p = 0.04) and angiogenesis (p = 0.04 and p = 0.006, respectively)." (PMID 36900270, 2023). "After antigen-presenting cells such as DCs are activated, they present tumour antigens to CD4+ T cells or CD8+ T cells, which are activated and proliferate into tumour-specific CTLs, enhancing the cytotoxic effects of the CD8+ T cells." (PMID 37261073, 2023). "At the single-cell level, ELOVL2 was expressed in tumor cells, cancer associated fibroblasts (CAFs) and smooth muscle cells (SMCs), while PLCG1 was presented in CD4+ and CD8+ T cells, as expected." (PMID 37483592, 2023). "We also observed a proportion of CD4+ TILs with a FoxP3+T-bet+ phenotype that increased during tumour outgrowth." (PMID 37153625, 2023). "Compared to CD8+ cytotoxic T cells, CD4+ T helper cells are much rarer within the tumour microenvironment." (PMID 37232837, 2023). "IGF1 has also been elucidated as a dictator CD4+ T cell by enhancing ERβ transcriptional activity and an immuno editor that eradicates new emerging tumor cells in the immune system." (PMID 36900213, 2023). "The novel multifaceted involvement of CD4+ T cells in the anti-tumor immune response has been reviewed along with their old paradigm in cancer." (PMID 38140230, 2023). "Reportedly, PTEN downregulation in the HCC mouse model reduced CD8+T cells infiltration in tumor tissue, along with increasing immunosuppressive Foxp3+CD4+CD25+Tregs and upregulating PD-L1 expression on tumor cells." (PMID 37007125, 2023). "The scRNA‐seq analysis highlighted cytotoxic CD4+ T cells exhibiting tumour‐specific states, clonally expanding in tumours and presenting lethality to autologous tumours." (PMID 37488671, 2023). "Further, in another phase 2 study (UMIN-CTR Clinical Trial Registry UMIN000015995), posttreatment biopsies revealed increasing tumor-infiltrating CD4+/CD8+ lymphocytes and persistently low numbers of Foxp3+ cells." (PMID 37444531, 2023). "A more detailed evaluation of the T-cell subpopulations in the tumor environment revealed that it is in fact the number of CD4+ Treg cells that predicts worse outcome in prostate cancer." (PMID 38062230, 2023). "The ratio of TNFα+ CD4+ and IL-17A+ CD4+ was also skewed towards more IL17A+ CD4+ in tumor compared with STM." (PMID 38074634, 2023). "Cytotoxic CD4+ T cells have attributes of anti-viral and anti-tumor effects, which are carried out by activating CD8+ T cells and B cells." (PMID 38090482, 2023). "Tumor cells are CD4+, although the CD4/CD8 ratio is usually preserved in lymph nodes involved by AITL." (PMID 37182145, 2023). "Further investigation is necessary to elucidate the role of CX3CR1+CD4+ T cells in tumor immune response." (PMID 37509302, 2023). "Both studies underscore the role of CD4+ T cell exhaustion in tumor progression and highlight the potential of CD4-targeted therapy." (PMID 38077321, 2023). "Tumor tissues of PC patients who undergo neoadjuvant therapy have elevated CD4+ and CD8+ TILs and a lower postoperative recurrence rate." (PMID 37529035, 2023).